KRAS (KRas proto-oncogene, GTPase)
Diseases named in the same sentence as KRAS in open-access papers (continued):
Sharing a sentence is not in itself a finding about the gene and the disease.
lung adenocarcinoma (continued). "EGFR and KRAS mutations were observed in 9 (14.1%) and 24 (37.5%) cases, respectively, in lung adenocarcinoma with smoking-related IP." (PMID 38611005, 2024). "As one of the most frequently mutated oncogene KRAS, it is frequently seen in pancreatic, colorectal, lung adenocarcinomas, and urogenital cancers and is recognized as the founder carcinogenic mutation in the genome." (PMID 38706597, 2024). "Mutations in the Kirsten rat sarcoma viral (KRAS) oncogene constitute a significant driver of lung adenocarcinoma, present in 10–40% of patients, which exhibit heterogeneous clinical outcomes, mainly driven by concurrent genetic alterations." (PMID 37490263, 2024). "We observed 7.6% of ERBB2 mutations in our LCINS, consistent with 2%-13% reported in other populations.1-4,6 In our series, only 5.9% of patients with lung adenocarcinoma had KRAS mutations, in accordance with other LCINS studies (4.4%-18%)." (PMID 38944844, 2024). "Earlier studies have indicated that patients with NSCLC carrying KRAS mutations exhibit elevated levels of YAP expression, and YAP1 silencing can enhance response to trametinib in human lung adenocarcinoma cells (MOR/CPR) encoding KRAS G12C." (PMID 38499647, 2024). "KRAS mutation, a common driver of lung adenocarcinoma, is associated with KEAP1 loss-of-function mutations in approximately 20% of KRAS mutant NSCLC cases, forming a KRAS-KEAP1 co-mutation (KK) type." (PMID 38566036, 2024). "KRAS mutations represent the most prevalent genetic driver alteration in lung adenocarcinomas (LUAD)." (PMID 38643157, 2024). "The prognostic role of KRAS mutations in lung adenocarcinoma has long been the subject of intensive studies." (PMID 38953007, 2024). "The KRASG12C substitution, occurring in 10–30% of lung adenocarcinoma cases and accounting for 40–50% of all KRAS mutations, is prevalent." (PMID 38611005, 2024). "In lung adenocarcinoma, key oncogenes such as KRAS, EGFR, ALK, ERBB2, and BRAF are frequently mutated and are found in over 50% of cases." (PMID 39682234, 2024). "The KRAS G12C mutation was present in 17% of lung adenocarcinoma cases and is targeted by mutation-specific selective covalent inhibition with adagrasib or sotorasib." (PMID 38890488, 2024). "Approximately 30% of patients with lung adenocarcinoma harbor KRAS mutations, which are most commonly G12C and G12V." (PMID 39718828, 2024). "Our case highlights the typical and dynamic changes in imaging features of P-ADC and provides an indicative treatment strategy for KRAS G12V-mutated lung adenocarcinoma." (PMID 38659041, 2024). "KRAS mutations were positively associated with men and longer tumor long diameters and negatively correlated with lung adenocarcinoma (P < 0.05 for all)." (PMID 39364008, 2024). "In another preclinical study, KRAS inhibition was associated with the transition of lung adenocarcinoma alveolar type 2 cells to alveolar type 1 (AT1) cells." (PMID 39301544, 2024). "Kirsten rat sarcoma viral oncogene homolog (KRAS) is the most frequently mutated oncogene in lung adenocarcinoma, with G12C and G12V being the most predominant forms." (PMID 39718828, 2024). "KRAS mutations are frequent in lung adenocarcinomas, accounting for 43% of cases, while NRAS and HRAS mutations account collectively for approximately 1.2% of cases." (PMID 39301544, 2024).
lung adenocarcinoma (continued). "First, we generated a library of lentiviral vectors encoding sgRNAs targeting 240 genes that are regulated by KRAS in human lung adenocarcinoma." (PMID 38635884, 2024). "KRAS/LKB1 co-mutated lung adenocarcinoma displays poor response to PD-1 blockade whereas the mechanism remains undetermined." (PMID 38291516, 2024). "Our previous in silico investigation using this screen indicated that lung adenocarcinoma cell lines harboring KRAS mutations are more sensitive to farnesyl-transferase inhibitors than those with wild-type KRAS." (PMID 38278976, 2024). "Our analysis of publicly available databases showed that lung adenocarcinoma cell lines harboring KRAS-G12C mutation tend to be more sensitive to FTis than KRAS wild-type cells." (PMID 38278976, 2024). "The earliest and most frequent mutations in lung adenocarcinoma occurs in the KRAS gene and affects the EGFR/RAS/RAF signaling pathway." (PMID 38953007, 2024). "KRAS mutations were positively associated with men and longer tumor long diameter and negatively associated with lung adenocarcinoma." (PMID 39364008, 2024). "While KRAS mutations are notably frequent in lung adenocarcinomas (14%) and colorectal tumors (5%), their dependence on the KRAS mutation seems to differ between these cancers." (PMID 38111008, 2023). "Our study involved a comprehensive comparison of feature selection and machine learning approaches to efficiently detect EGFR and KRAS mutations in patients with lung adenocarcinoma using radiomic features extracted from CT images." (PMID 37508774, 2023). "This study showed that radiomic features can be associated with EGFR and KRAS mutational status in patients with lung adenocarcinoma." (PMID 37508774, 2023). "Most somatic mutations of the EGFR gene associated with lung adenocarcinoma cause abnormal expression of the KRAS gene, which can continuously activate the EGFR signaling pathway and eventually enhance cell proliferation, leading to the generation of cancer." (PMID 37372185, 2023). "In lung adenocarcinomas with KRAS mutations, RAF1 ablation in tumors leads to significant regressions including some complete regressions." (PMID 38137485, 2023). "In the MSK‐Impact study, the KRAS mutation positivity rate was 33.2% in 1586 lung adenocarcinoma cases." (PMID 37751775, 2023). "This study reports a patient with untreated lung adenocarcinoma, characterized by a KRAS G12C mutation, which transformed into SCLC before treatment." (PMID 37131995, 2023). "Here, the authors use a KRAS signature drug repurposing screen and identify the multityrosine kinase PKC inhibitor Midostaurin as synergistic with MEK and KRAS inhibitors in KRAS-mutated lung adenocarcinoma." (PMID 37816716, 2023). "This was a retrospective study of mostly adenocarcinoma patients, of which 56% had a KRAS mutation, compared to ~ 38% in the Norwegian lung adenocarcinoma population." (PMID 37434111, 2023). "The KRAS(G12C) mutation is the most common genetic mutation in North American lung adenocarcinoma patients." (PMID 36845684, 2023). "In agreement, a recent meta-analysis suggested that KRAS mutations are associated with poor survival outcomes, especially in patients with lung adenocarcinoma and stage I disease." (PMID 36768704, 2023). "Among other crucial alterations, RAS (KRAS, NRAS, HRAS) gene mutations are found in approximately 27% of all cancers, with high frequency of KRAS mutations in pancreatic duct adenocarcinoma, lung adenocarcinoma." (PMID 37427115, 2023). "KRAS mutation status is positively correlated with CD47 expression in several lung adenocarcinoma cohorts." (PMID 36413402, 2023). "Here, we aimed to evaluate the prognostic impact of EGFR and KRAS mutations by considering the relationship between these mutations and their histological subtype and/or tumor invasion status in resected pTis-3N0M0 lung adenocarcinoma." (PMID 36918771, 2023).
lung adenocarcinoma (continued). "In this retrospective study, we examined 103 patients with KRAS-mutant lung adenocarcinoma who were treated with immunotherapy-based regimens and we evaluated the clinical outcomes according to PD-L1 expression and the type of KRAS mutation." (PMID 37916173, 2023). "Despite these findings, this study did observe that KRAS mutations were found more frequently in Lung Adenocarcinoma (LUAD), a common histological form of NSCLC, and were more common in current and former smokers." (PMID 37082203, 2023). "In KRAS mutant lung adenocarcinoma heterozygous loss of the wild type allele is very frequent (∼75%) leaving the mutant allele the only functioning KRAS (a kind of homozygosity), whereas the copy gains of the mutant allele is much less frequent." (PMID 38239281, 2023). "Previous studies have shown that patients with stage I lung adenocarcinoma and KRAS mutations have a significantly higher risk of recurrence than those without the mutation." (PMID 36768704, 2023). "For example, approximately 30% of lung adenocarcinomas harbor KRAS mutations, with KRASG12C being the most common subtype (12%–15%)." (PMID 36413402, 2023). "This set of LUAD samples was chosen to represent important biological differences of high relevance to lung adenocarcinoma, as five samples were driven by KRAS mutations and five by EGFR mutations." (PMID 37012232, 2023). "KRAS is another major somatic variant in lung adenocarcinoma, and a therapeutic agent for KRAS G12C became available in clinical settings." (PMID 36918771, 2023). "In NSCLC, KRAS mutations are seen in about 30% of lung adenocarcinomas and 5% of squamous lung cancers, in 26% of Westerners and 11% of Asians, and also in 30% of smokers and 10% of nonsmokers." (PMID 36675641, 2023). "Our present study combined FDG-PET radiomics with machine learning to establish and validate a clinical prediction model evaluating KRAS mutation status in lung adenocarcinoma." (PMID 37509345, 2023). "A study of lung adenocarcinoma patients found that KRAS mutations were significantly associated with older age (>45 years old) at diagnosis." (PMID 36675641, 2023). "We selected patients with stage IV KRAS-mutated lung adenocarcinoma diagnosed in 2019 to 2020 who received first-line (chemo-)immunotherapy." (PMID 37674812, 2023). "Of note, the KRAS G12C mutation is relatively high in lung adenocarcinoma than in pancreatic adenocarcinoma patients." (PMID 37396909, 2023). "Overall, this study demonstrated the potential of radiomic features and machine learning in predicting EGFR and KRAS mutations in lung adenocarcinoma patients." (PMID 37508774, 2023). "Approximately 20% of lung adenocarcinomas harbor activating mutations at KRAS, an oncogene with the ability to alter the tumor immune microenvironment." (PMID 37916173, 2023). "About 25–30% of lung adenocarcinomas develop KRAS mutations, with the KRAS-G12C point mutation being the most common." (PMID 37834062, 2023). "To further explore the clinical relevance of our findings, we assessed the correlation of KRAS mutation status with CD47 expression in 3 independent lung adenocarcinoma cohorts." (PMID 36413402, 2023). "KRAS-mutant lung adenocarcinoma cells are susceptible to SLC7A11 inhibitor-induced cell death, resulting in attenuated tumor growth in vivo." (PMID 37161053, 2023). "In this study, we showed that oncogenic KRAS mutations interact with the innate immune system in the context of lung adenocarcinoma progression by promoting tumor cell evasion from macrophage phagocytosis." (PMID 36413402, 2023).
lung adenocarcinoma (continued). "Our retrospectively developed model demonstrates good predictive accuracy for determining the KRAS mutation status in lung adenocarcinoma patients." (PMID 37509345, 2023). "A549 is a well-established human lung adenocarcinoma cell line that contains wild-type EGFR (epidermal growth factor receptor) but a homozygous G12S KRAS mutation." (PMID 37239373, 2023). "The ubiquitin-proteosome and DNA replication pathways were altered in KRAS-mutated and triple-negative molecular subtypes of lung adenocarcinoma after HSP90 inhibition." (PMID 37762133, 2023). "For instance, the KRAS-G12C mutation is associated with poorer outcomes in surgically resected lung adenocarcinoma than wild-type KRAS." (PMID 37925409, 2023). "In summary, these results from 3 independent lung adenocarcinoma cohorts were consistent with each other and confirmed that KRAS mutation status is positively correlated with CD47 expression in patients with lung adenocarcinoma." (PMID 36413402, 2023). "This retrospective study aimed to develop a clinical prediction model that combines clinical–pathological variables and radiomics derived from PET scans to assess the KRAS mutation status in patients with lung adenocarcinoma." (PMID 37509345, 2023). "Our retrospectively established model shows high performance in predicting KRAS mutation status in lung adenocarcinoma." (PMID 37509345, 2023). "STK11/LKB1 mutations have been found to cause primary resistance to PD-1/PD-L1 inhibitors in patients with KRAS-mutated lung adenocarcinoma." (PMID 36675641, 2023). "We evaluated the prognostic impact of EGFR and KRAS mutations by considering other clinicopathological recurrence risks in resected pTis-3N0M0 lung adenocarcinoma." (PMID 36918771, 2023). "As well as EGFR mutation, KRAS mutation is also major targetable somatic variable in primary lung adenocarcinoma." (PMID 36918771, 2023). "Another study of advanced lung adenocarcinoma showed that patients with KRAS mutations of all gene mutations had the best response to immunotherapy." (PMID 36675641, 2023). "Approximately 26.1% of patients diagnosed with lung adenocarcinoma harbour a KRAS mutation, which is associated with a poorer prognosis." (PMID 37509345, 2023).
lung adenocarcinoma (continued). "Overexpression of SLC7A11 in KRAS-mutant lung adenocarcinoma (LUAD) patients is linked to increased susceptibility to SLC7A11 inhibition in cells carrying KRAS-mutant LUAD, which significantly reduces cystine uptake and intracellular glutathione biosynthesis." (PMID 37845218, 2023). "In another study involving 536 patients with KRAS-mutant lung adenocarcinoma, both STK11 and KEAP1 mutations in the presence of a KRAS mutation were associated with poor response rates to anti-PD-L1 inhibitors." (PMID 37662925, 2023). "In this paper, we presented an explainable radiogenomic workflow to characterize EGFR and KRAS mutations from the CT scans of lung adenocarcinoma patients." (PMID 37508774, 2023). "SETD2 inactivation leads to heightened mTORC1 signaling, oxidative metabolism and protein synthesis in KRAS-driven mouse models of lung adenocarcinoma, contributing to the understanding of how SETD2 deficiency drives early and widespread tumor growth." (PMID 36899051, 2023). "Mutations in LKB1 commonly co-occur with activating KRAS mutations (often referred to as “KL tumors”) comprising 7-10% of lung adenocarcinoma patients." (PMID 37035141, 2023). "KRAS mutation, detected mainly in smokers with lung adenocarcinoma, is associated with a poor disease prognosis and poor response to systemic and molecular therapy." (PMID 37893442, 2023). "G12C was observed in the high-risk group, which is coherent with the KRAS-G12C as a major driver in lung adenocarcinoma with smoking." (PMID 36936374, 2023). "In KRAS‐mutated lung adenocarcinoma, the use of the MEK inhibitor trametinib leads to abnormal activation of FGFR1, which leads to the development of drug resistance." (PMID 37750089, 2023). "From Japan, the prevalence of KRAS mutations based on Oncomine DxTT with tissue specimens was reported to be 14.1% in lung adenocarcinoma cases." (PMID 37751775, 2023). "Specifically, KRAS mutations are associated with resistance to conventional chemotherapy drugs used for lung adenocarcinoma." (PMID 37508774, 2023). "Our previous work has demonstrated that hyperactivation of ERK2 is toxic to lung adenocarcinoma cells bearing KRAS or EGFR oncogenic mutations." (PMID 36418460, 2022). "Recently, allosteric inhibitors that covalently bind to KRAS G12C mutations have been approved for use in lung adenocarcinomas." (PMID 34990404, 2022). "RAS84 captures RAS oncogenic activity in tumour samples better than the mutational status of KRAS when applied to cohorts of lung adenocarcinoma patients and other cancer types." (PMID 36163168, 2022). "The therapeutic efficacy of COMP7 in vivo was also tested using a patient-derived xenograft model of lung adenocarcinoma (LUAD) harboring the KRAS(G12V) mutation (LUAD-PDX/KRAS)." (PMID 36377663, 2022). "A recent research implicated that the diversity of KRAS-mutant lung adenocarcinomas (LUADs) is associated with different characters, such as KRAS dependency, immunogenicity, and STK11/KEAP1 comutations." (PMID 35945957, 2022). "Deregulation of the Ras pathway by an activating Kirsten rat sarcoma viral oncogene (KRAS) mutation, occurring in about 30% of lung adenocarcinoma patients, is a hallmark of NSCLC." (PMID 35574381, 2022). "To evaluate the antitumor activity of FX1 + etoposide in a more clinically relevant mouse model, we established a patient-derived xenograft model of lung adenocarcinoma harboring a G12V mutation in KRAS (LACPDX)." (PMID 35503721, 2022). "A growing body of literature supports our observation that lung adenocarcinomas mutated for KRAS and with an activated NRF2 pathway have an altered tumor microenvironment that can, in part, be attributed to changes in tumor metabolism." (PMID 35626147, 2022).